SDHA (succinate dehydrogenase complex flavoprotein subunit A)
Description:
Flavoprotein (FP) subunit of succinate dehydrogenase (SDH) that is involved in complex II of the mitochondrial electron transport chain and is responsible for transferring electrons from succinate to ubiquinone (coenzyme Q). SDH also oxidizes malate to the non-canonical enol form of oxaloacetate, enol-oxaloacetate (By similarity). Enol-oxaloacetate, which is a potent inhibitor of the succinate dehydrogenase activity, is further isomerized into keto-oxaloacetate (By similarity). Can act as a tumor suppressor.
Synonyms: Fp; SDH2; SDHF; CMD1GG; MC2DN1; NDAXOA; PGL5; PPGL5; SDH1
Tractability: Small molecule: a structure with a bound ligand is known. Antibody: UniProt places it where antibodies can reach, with high confidence. PROTAC: ubiquitination databases record sites on it; its protein half-life has been measured; a small molecule that binds it is known.
Target class: Enzyme; Oxidoreductase
Gene: Protein-coding gene on chromosome 5 (218,274 to 257,083, forward strand). Ensembl gene ENSG00000073578.
Subcellular location: Mitochondrion inner membrane
Subcellular location (Human Protein Atlas): Mitochondria; Plasma membrane
Pathways (Reactome):
Metabolism: Citric acid cycle (TCA cycle); Maturation of TCA enzymes and regulation of TCA cycle; Respiratory electron transport
Gene Ontology:
Molecular function: protein binding; succinate dehydrogenase (quinone) activity; electron transfer activity; FAD binding; flavin adenine dinucleotide binding; oxidoreductase activity; oxidoreductase activity, acting on the CH-CH group of donors
Biological process: nervous system development; respiratory electron transport chain; succinate metabolic process; mitochondrial electron transport, succinate to ubiquinone; proton motive force-driven mitochondrial ATP synthesis; tricarboxylic acid cycle; electron transport chain
Cellular component: mitochondrial inner membrane; mitochondrion; respiratory chain complex II (succinate dehydrogenase); mitochondrial matrix; membrane
Genetic constraint (gnomAD): Loss-of-function variants: 41 observed, 67.71 expected, observed/expected ratio (o/e) 0.61, 90% interval 0.47 to 0.79. The upper end of that interval is the gene's LOEUF score, 0.79, which puts it in group 3 of 6, group 1 being the genes least tolerant of losing a copy. Missense variants: 642 observed, 823.17 expected, observed/expected ratio (o/e) 0.78, 90% interval 0.73 to 0.83. Synonymous variants: 314 observed, 324.05 expected, observed/expected ratio (o/e) 0.97, 90% interval 0.88 to 1.06.
Gene-disease validity (ClinGen):
ClinGen rates the evidence that SDHA causes each of these diseases.
hereditary pheochromocytoma-paraganglioma (autosomal dominant): Definitive. Neoplasm predisposition characterized by an increased risk of paragangliomas (tumors that arise from neuroendocrine tissues distributed along the paravertebral axis from the base of the skull to the pelvis) and pheochromocytomas (paragangliomas that are confined to the adrenal medulla).
mitochondrial disease (autosomal recessive): Definitive.
Leigh syndrome (autosomal recessive): Moderate. A progressive neurological disease defined by specific neuropathological features associating brainstem and basal ganglia lesions.
mitochondrial disease (autosomal dominant): Limited.
Cancer hallmarks: angiogenesis (suppresses); change of cellular energetics (promotes)
Homologues: Orthologues: chimpanzee SDHA (99% identical), macaque SDHA (97% identical), dog SDHA (96% identical), rabbit SDHA (95% identical), mouse Sdha (95% identical), pig SDHA (94% identical), guinea pig SDHA (92% identical), rat Sdha (92% identical), tropical clawed frog sdha (86% identical), zebrafish sdha (83% identical), Drosophila melanogaster SdhA (74% identical), Caenorhabditis elegans sdha-1 (69% identical), and 1 more.
Diseases named in the same sentence as SDHA in open-access papers:
SDHA is named in the same sentence as 178 diseases in open-access papers, as found by Europe PMC text mining. Sharing a sentence is not in itself a finding about the gene and the disease. The quoted sentences say what the papers report.
paraganglioma (61 papers, 2005 to 2026). A benign or malignant neoplasm arising from paraganglia located along the sympathetic or parasympathetic nerves. "Germline pathogenic variants (PGVs) in the SDHA gene are also found in individuals with wild-type gastrointestinal stromal tumours (GISTs) and paragangliomas." (PMID 41635891, 2026). "Mutations in the gene encoding SDHA that result in altered SDHA function have been associated with the appearance of tumors such as paragangliomas and pheochromocytomas, gastrointestinal stromal tumors, renal cell carcinomas, and pituitary adenomas." (PMID 40141095, 2025). "SDHA mutations are related to the onset of neurodegenerative diseases and are associated with the etiology of paraganglioma (PGL) and gastrointestinal stromal tumor (GIST)." (PMID 39669196, 2024). "Another patient was found to carry an SDHA variant associated with risk for paraganglioma and pheochromocytomas." (PMID 36820377, 2023). "To date, only a few cases report SDHA germline mutation in the context of other tumors: paraganglioma in one case, pulmonary chondroma in two cases, and the full Carney triad in one patient." (PMID 36980917, 2023). "SDHA pathogenic germline variants (PGVs) are identified in up to 10% of patients with paraganglioma and phaeochromocytoma and up to 30% with wild-type gastrointestinal stromal tumours." (PMID 35260474, 2023). "The association of pheochromocytoma–paraganglioma and GISTs, the so-called Carney–Stratakis syndrome, occurs more frequently in carriers of SDHA and SDHD variants." (PMID 37046734, 2023). "As a tumor suppressor gene, SDHA is more likely to be associated with neuroendocrine related cancers, more commonly paragangliomas, with germline mutations accounting for 7.6% of patients with this cancer type." (PMID 37296477, 2023). "We also identified higher ratio of the pseudohypoxia subtype, which enriched for SDHA/SDHB mutations in TCGA paraganglioma and pheochromocytoma AYAs." (PMID 36433963, 2022). "Germline mutations in SDHx are a major cause of phaeochromocytoma and paragangliomas but inheritance patterns and risks differ between genes, and the penetrance of germline SDHA mutations is much lower than for SDHB, SDHC or SDHD." (PMID 35441217, 2022). "Pathogenic germline variants in the succinate dehydrogenase A (SDHA) gene are associated with paraganglioma and pheochromocytoma." (PMID 35875079, 2022). "Individuals with known pathogenic variants in SDHA are recommended to receive annual biochemical and clinical surveillance for signs and symptoms of paraganglioma and pheochromocytoma syndrome." (PMID 33960148, 2021). "Approximately 20% of patients diagnosed with a phaeochromocytoma or paraganglioma carry a germline mutation in one of the succinate dehydrogenase (SDHx) genes (SDHA, SDHB, SDHC and SDHD), which encode the four subunits of the SDH enzyme." (PMID 34021277, 2021). "SDHA pathogenic variants increase the risk of paraganglioma, pheochromocytoma, GIST, pituitary adenoma and renal cancer in an autosomal dominant inherited condition named paraganglioma syndrome type 5." (PMID 31413764, 2019). "To assess the clinical relevance of our findings, we inspected tumor tissue from paraganglioma patients with SDHA and SDHB mutations, as well as sporadic paraganglioma patients." (PMID 29880867, 2018). "In vitro experiments are further corroborated by analysis of paraganglioma tissues from patients with sporadic, SDHA and SDHB mutations." (PMID 29880867, 2018). "The mutation mapped to the fumarate reductase C-terminal of SDHA, a catalytic domain in which germline mutations have been reported to be deleterious in patients presenting paragangliomas and pheochromocytomas as well as Leigh syndrome." (PMID 28878254, 2017). "Subsequently, germline mutations in SDHA were found in many paragangliomas including those of vagal origin." (PMID 28187001, 2017).
paraganglioma (continued). "Germline mutations within any of its four subunits (SDHA, B, C and D) have been associated with development of a number of tumors, including pheochromocytoma and/or paraganglioma, gastrointestinal stromal tumors, renal cancer, and pituitary adenomas." (PMID 28738844, 2017). "Significantly, germline SDHA mutations, described in patients bearing GISTs or paragangliomas and in paraganglioma/pituitary adenoma familial associations, are unreported in CSS, possibly due to their low penetrance." (PMID 27437068, 2016). "Here we introduce all reported paraganglioma and pheochromocytoma related sequence variations in these genes, in addition to all reported mutations of SDHA." (PMID 16288654, 2005). "Finally, SDHAF2, a gene that plays an essential role in the assembly of SDH and the flavination of the SDHA subunit, was found to be mutated in familial and sporadic paraganglioma and pheochromocytoma." (PMID 34200553, 2021). "SDHA is a tumor suppressor and is implicated in paraganglioma and gastrointestinal stromal tumors." (PMID 30704450, 2019). "However, two recent studies allowed the identification of SDHA germline mutations in at least 3% patients with apparently sporadic cases of paraganglioma or pheochromocytoma." (PMID 22974104, 2012). "Paraganglioma (PGL) is often linked with MEN, and its occurrence is commonly associated with metabolism-related mutation genes, which currently include SDHA, SDHB, SDHC, SDHD, and SDHAF2." (PMID 39591360, 2024). "The study identifies the importance of positron emission tomographic (PET) and anatomic imaging modalities and their individual performances in detecting succinate dehydrogenase A (SDHA)-related metastatic pheochromocytoma and paraganglioma (PPGL)." (PMID 36010880, 2022). "Germline mutations in SDHA, SDHB, SDHC, and SDHD (collectively, SDHx) are associated with the development of PRL- and GH-secreting adenomas, pheochromocytomas, and/or paragangliomas, a syndrome named 3P association." (PMID 35743266, 2022). "VHL, RET, NF1, SDHB, and SDHD are major susceptibility genes, accounting for 90% of familial pheochromocytomas/paragangliomas, whereas TMEM127, SDHA, SDHC, SDHAF2, and MAX are minor susceptibility genes responsible for 10% of these tumors." (PMID 30456751, 2018). "Germline mutations in the four genes encoding SDH subunits (SDHA, SDHB, SDHC and SDHD) are linked to the development of neuroendocrine tumors such as pheochromocytomas and paragangliomas." (PMID 28911113, 2017). "Mutations in the CII subunit genes SDHA, SDHB, SDHC and SDHD have also been associated with paragangliomas and pheochromocytoma." (PMID 26839416, 2016). "At the expression level, most studies utilized immunohistochemistry to measure SDHA and SDHB protein, and showed loss of SDHB in pheochromocytoma–paraganglioma tumors." (PMID 25694510, 2015). "The long-sought link between SDHA gene and paraganglioma development was only unveiled in 2010, when a patient with an extra-adrenal paraganglioma was found to have an SDHA missense mutation." (PMID 24899893, 2014). "In the same year, mutations in the SDHAF2 (SDH5) gene encoding a protein necessary for the flavination of the subunit SDHA were detected in patients with paraganglioma." (PMID 22995659, 2012). "Heterozygous germline mutations in SDHA, SDHB, SDHC, and SDHD cause hereditary paragangliomas and pheochromocytomas, and germline mutations in SDHB and SDHC were found to be associated with gastrointestinal stromal tumors." (PMID 22995659, 2012). "Additionally, studies have pinpointed SDHA as a potential tumor suppressor in various cancers, including hepatocellular cancer and paraganglioma." (PMID 40119440, 2025).
paraganglioma (continued). "Neither the 24 SDHB-related cases nor the 2 SDHA variant carriers developed a paraganglioma after a median of 4.83 and 5.92 years of follow-up, respectively." (PMID 39881751, 2025). "Overall, patients with SDHA-mutant tumors tend to have an older median age compared to the SDH-deficient GISTs due to other subunit mutations, while SDHB, SDHC, and SDHD mutant GISTs usually also develop paragangliomas." (PMID 36980917, 2023). "Indeed, it was shown that mutations in SDHA account for around 30% of all KIT/PDGFRA-WT GIST, while being responsible for <1% of all pheochromocytoma and paraganglioma cases (PPGL), as opposed for example to SDHB that accounts for about 10% of all PPGL." (PMID 35059314, 2021). "Subsequently, SDHA and SDHB mutations were said to cause pheochromocytoma and paraganglioma." (PMID 34200553, 2021). "SDHAF2 mutations may present similarly to mutations in SDHA, SDHB, SDHC and SDHD as paraganglioma and pheochromocytoma." (PMID 26839416, 2016). "The few SDHA-affected individuals described so far have presented with distinct phenotypic characteristics: pheochromocytoma, sympathetic (abdominal and thoracic), and parasympathetic head and neck paragangliomas." (PMID 24899893, 2014). "Although homozygous mutations in SDHA have been found in Leigh syndrome, a severe neurodegenerative disorder of childhood, and with neuromusculopathies, no genetic link between SDHA and paraganglioma susceptibility has ever been established." (PMID 17376234, 2007). "This aggregate result underscores the different tumor spectrum of SDHA-germline variant carriers and Carney Stratakis Syndrome patients, which are known to harbor SDHB, SDHC, or SDHD mutations, and to develop invariably the association of GIST and paraganglioma during their life course." (PMID 35059314, 2021). "In addition to their role in primary mitochondrial disease, heterozygous germline variants in other complex II subunits and assembly factors (including SDHA, SDHB, SDHC, SDHD and SDHAF2) are associated with paragangliomas, phaeochromocytomas and gastrointestinal stromal tumours." (PMID 34012134, 2021). "Up to now, the onset of other tumor types in the context of SDHA-mutant GIST appears to be very rare and limited to the concurrent description of paraganglioma in one case, of pulmonary chondroma in two cases, and of the full Carney triad in one patient." (PMID 35059314, 2021). "SDHA, SDHAF2, SDHB, SDHC, SDHD, MAX, and TMEM127 genes are offered to be analyzed for the diagnosis of paraganglioma/pheochromocytoma (PGL/PCC) syndromes." (PMID 33777662, 2021). "Germline defects in SDH, particularly in SDHA and SDHB, have been detected in several tumor types, including pheochromocytomas, paragangliomas, GISTs, and renal cell carcinomas." (PMID 23888270, 2013). "First, it complements the prior SDHA-related report by documenting a distinct genotype with the same cross-lineage pattern, namely, non-epithelial paraganglioma and epithelial NET arising in the same individual." (PMID 41426878, 2025). "The syndromic presentation of HNPGLs is associated with mutations in SDHD (paraganglioma syndrome type 1, PGL1), SDHAF2 (PGL2), SDHC (PGL3), SDHB (PGL4), SDHA (PGL5), VHL (von Hippel–Lindau syndrome), HIF-2α (paraganglioma–somatostatinoma–polycythemia), and NF1 (neurofibromatosis type 1 syndrome)." (PMID 39684472, 2024). "We hypothesize that inhibited R662 methylation in the R662C mutant disrupts SDHA flavinylation, complex maturation, and/or SDH complex stability, contributing to MCIID pathogenesis and paragangliomas." (PMID 36830724, 2023). "Further, SDHA-mutated paragangliomas lacked FAD, a cofactor of CII associated with the catalytic subunit SDHA, while it was detected in sporadic paragangliomas or those with SDHB mutations." (PMID 29880867, 2018).
paraganglioma (continued). "The persistent expression of SDHA protein in SDHA non-mutated GIST is in accordance with previous studies which showed consistent SDHA protein expression in SDHB-, and SDHD-mutated paraganglioma." (PMID 22974104, 2012). "In fact, no paragangliomas occurred at all during the follow-up of the SDHA and SDHB group." (PMID 39881751, 2025). "We could not include other paraganglioma genes like SDHA, SDHC, MAX, etc., and we did not include NF1 carrier cases in this study." (PMID 33777662, 2021). "In a study of 972 cases from the European-American-Asian Pheochromocytoma and Paraganglioma Registry without mutations in the common PPGL genes, 58 had mutations in less commonly mutated genes (SDHA, TMEM127, SDHAF2) including 8 cases of PCC with MAX mutations." (PMID 31666924, 2019).
pheochromocytoma (55 papers, 2005 to 2026). "Heterozygous SDHA LoF variants cause the pheochromocytoma/paraganglioma syndrome and lead to the accumulation of the oncometabolite succinate with various cellular consequences, e.g., on HRR." (PMID 41546701, 2026). "Seventeen pathogenic variants of SDHA cause MCIID, and SDHA mutations can also induce familial paragangliomas and pheochromocytomas." (PMID 36830724, 2023). "SDHB and SDHD mutations are common in pheochromocytoma/paraganglioma, and SDHA mutations and SDHC promoter hypermethylation are relatively common in GISTs4." (PMID 30971719, 2019). "Genomic analysis of familial PGL/pheochromocytoma (PCC) has shown that while mutations of SDHD and SDHC are associated with PGL1 and PGL3, mutations in the large subunit genes SDHB, SDHA and SDHAF2 are associated with PGL4, PGL5 and PGL2." (PMID 35382567, 2022). "Familial CPGLs occur as hereditary paraganglioma/pheochromocytoma (PGL/PCC) syndromes, including PGL1, PGL2, PGL3, PGL4, and PGL5, which are associated with germline mutations in the SDHD, SDHAF2, SDHC, SDHB, and SDHA genes, respectively." (PMID 32971818, 2020). "The homozygous/compound heterozygous mutations in SDHA result in rigorous neurological dysfunction and cardiomyopathy, but heterozygous germline mutations in SDHB-D cause a pheochromocytoma-PGL syndrome." (PMID 31372201, 2019). "Germline mutations in the succinate dehydrogenase (SDHA, SDHB, SDHC, SDHD, SDHAF2) or Von Hippel-Lindau (VHL) genes cause hereditary paraganglioma/pheochromocytoma." (PMID 28099933, 2017). "Mutations in SDHAF1 and SDHA lead to encephalomyopathy and leukoencephalopathy, while variants in SDHA, SDHB, SDHC, SDHD and SDHAF2 are responsible for hereditary paraganglioma and pheochromocytomas, rare neuroendocrine tumors." (PMID 33435522, 2021). "Cluster 1 PPGLs include pheochromocytomas and abdominal paragangliomas carrying the highest risk of metastatic spread, especially the TCA cycle aberrant tumors carrying genetic variants in enzymes regulating the TCA cycle, including SDHA, SDHB, SDHAF2, FH, MDH2, ISH1 and SLC25A11." (PMID 35205664, 2022). "The major mutations associated with pheochromocytoma are von Hippel-Lindau gene (VHL), REarranged during Transfection (RET) proto-oncogene, neurofibromatosis type 1 gene (NF1), genes encoding four succinate dehydrogenase complex subunits (SDHx; i.e., SDHA, SDHB, SDHC, and SDHD genes)." (PMID 35932074, 2022). "Familial HNPGLs together with pheochromocytomas (PCCs) account for about 40% and are associated with four types of hereditary paraganglioma syndromes (PGL1–5) caused by mutations in the following genes: SDHD (PGL1), SDHAF2 (PGL2), SDHC (PGL3), SDHB (PGL4), and SDHA (PGL5)." (PMID 33391357, 2020). "In this study, we examined the expression of SDHA and SDHB in canine pheochromocytomas and compared these with data on patient age, tumor size, and invasion, in order to determine the utility of SDH IHC in canine pheochromocytoma diagnostics." (PMID 32957698, 2020). "In contrast, mutations of SDHA result in a range of clinical phenotypes, including Leigh syndrome, but have never been reported in relation to HN PGL or pheochromocytoma." (PMID 16288654, 2005).